FABP5P3 (fatty acid binding protein 5 pseudogene 3)
Description:
High specificity for fatty acids.
Synonyms: TCAG_1781704; formerly FABP5L3
Gene: Transcribed processed pseudogene on chromosome 7 (152,442,543 to 152,442,950, forward strand). Ensembl gene ENSG00000241735.
Diseases named in the same sentence as FABP5P3 in open-access papers:
FABP5P3 is named in the same sentence as 3 diseases in open-access papers, as found by Europe PMC text mining. Sharing a sentence is not in itself a finding about the gene and the disease. The quoted sentences say what the papers report.
psoriasis (2 papers, 2023 to 2024). An autoimmune condition characterized by red, well-delineated plaques with silvery scales that are usually on the extensor surfaces and scalp. "Several lncRNAs are upregulated in psoriasis, such as MSX2P1, XIST, FABP5P3, KLDHC7B-DT, or SPRR2C, whereas MEG3, GAS5, PRINS or NEAT1 are downregulated in psoriasis." (PMID 38256115, 2024). "Other upregulated lncRNA in psoriasis are MIR31HG, MSX2P1, XIST, FABP5P3, KLDHC7B-DT, or SPRR2C; whereas, MEG3, GAS5, PRINS or NEAT1 are downregulated in psoriasis." (PMID 37628670, 2023).
renal fibrosis (1 paper, 2023). A final common manifestation of a wide variety of chronic kidney diseases characterized by glomerulosclerosis and tubulointerstitial fibrosis. "Consequently, FABP5P3 reversed TGFβ1-induced FAO suppression in proximal tubular epithelial cells and ultimately alleviated renal fibrosis." (PMID 38002328, 2023). "In kidney, FABP5P3 could improve TGFβ1-stimulated deregulation of fatty acid oxidation (FAO) and renal fibrosis." (PMID 38002328, 2023).
FABP5P3 also shares sentences with these, for which no sentence is quoted: hepatocellular carcinoma (1 paper).